BRCA1 (BRCA1 DNA repair associated)
Diseases named in the same sentence as BRCA1 in open-access papers (continued):
Sharing a sentence is not in itself a finding about the gene and the disease.
ovarian carcinoma (continued). "It is important to identify BRCA1 and BRCA2 pathogenic variants in ovarian cancer because they are therapeutic targets for olaparib therapy." (PMID 29997359, 2018). "Several cancers like TNBCs and ovarian cancers with mutant BRCA1 exhibit sensitivity to PARP inhibitors." (PMID 30647872, 2018). "BRCA1/2 mRNA expression levels have been previously investigated in women with breast and ovarian cancers, suggesting that they correspond with survival rates or chemotherapeutic sensitivity." (PMID 30622513, 2018). "Causative variants in BRCA1 and BRCA2 are well-established risk factors for breast and ovarian cancer." (PMID 29492181, 2018). "Given the limitations in early diagnosis and treatment of BRCA1/2-driven breast and ovarian carcinomas, prophylactic surgery is considered to be a standard option for clinical management of BRCA1/2 mutation carriers." (PMID 30211169, 2018). "Constitutional loss-of-function pathogenic variants in the tumor suppressor genes BRCA1 and BRCA2 are widely known to confer an elevated risk of breast and/or ovarian cancer, and their mutational screening has become a standard in routine diagnostic practice." (PMID 30441849, 2018). "We have reported the findings of a methodical review of reported germline variants in BRCA1, BRCA2, and other high-penetrance breast and ovarian cancer susceptibility genes within women of Indian descent." (PMID 35693198, 2018). "In case of ovarian cancer, BRCA1 and BRCA2 patients exhibit a differential age of tumor development—BRCA1 carriers develop tumors earlier than those carrying BRCA2 mutations (48 vs. 57 years)." (PMID 29459887, 2018). "In the BRCA1-mutant carrier, breast and ovarian cancers are the predominant abnormalities in whole-body haploinsufficiency." (PMID 30652068, 2018). "Mutations in BRCA1 and BRCA2, tumor suppressor genes, are found in about 50% and 70% of ovarian cancer patients with a family history of ovarian cancer, but 95% of ovarian cancer cases are sporadic." (PMID 30134520, 2018). "We have described genetic variants in BRCA1 and BRCA2 from tumors of Northeast Mexican patients with sporadic ovarian cancer." (PMID 29997359, 2018). "Similar to BRCA1 mutations, BARD1 mutations also lead to increased risk of triple negative breast cancer and ovarian cancer." (PMID 29686231, 2018). "The aim of this study was to describe genetic variants in the BRCA1 and BRCA2 genes in tumors from Northeast Mexican patients with sporadic ovarian cancer and to detect the percentage of potential eligible patients for future olaparib clinical trials." (PMID 29997359, 2018). "Defects in HR proteins, specifically BRCA1 and -2, lead to the failure of dsDNA break repair and increase the likelihood of breast and ovarian cancer." (PMID 29641431, 2018). "Much clinical evidence shows the presence of secondary mutations that functionally restore BRCA1 and BRCA2 proteins in platinum-resistant ovarian tumors, and also in BRCA1/2-mutated ovarian carcinomas that are resistant to olaparib." (PMID 30347758, 2018). "We found that 5 out of 67 (7.5%) breast and 13 out of 82 (15.8%) ovarian cancer patients tested positive for BRCA1 promoter methylation." (PMID 30049288, 2018). "Out of a pool of 367 breast/ovarian cancer families Sanger‐sequenced for BRCA1 and BRCA2 gene mutations, we selected a cohort of 20 BRCA1/2‐negative families to be subjected to the BROCA‐Cancer Risk Panel massive parallel sequencing." (PMID 29271107, 2018).
ovarian carcinoma (continued). "In epithelial ovarian cancer, low let-7e (21-nucleotide regulatory microRNA) leads to activation of BRCA1 and Rad 51 (339-amino acid protein that plays a major role in homologous recombination of DNA during double strand break repair)." (PMID 29932172, 2018). "While the number of family members tested for each BRCA1 or BRCA2 positive ovarian cancer patient increased following the educational campaign, the mean number of family members tested was 3.27 following the campaign." (PMID 29506471, 2018). "BRCA1 and BRCA2 germ line mutations increase breast and ovarian cancer susceptibility in heterozygous carriers." (PMID 28729482, 2017). "The three probands of BRCA1 deletion (1%) represented both familial risk and personal or clinicopathological risk factors as two with TNBC and one with bilateral ovarian cancer." (PMID 28205045, 2017). "Women who carry a pathogenic mutation in the BRCA1 or BRCA2 gene are at high risk of developing breast and ovarian cancers." (PMID 28376175, 2017). "The protein product of the breast and ovarian cancer gene, BRCA1, is part of an obligate heterodimer with BARD1." (PMID 28032817, 2017). "BRCA1/2 mutations demonstrated both OS and PFS benefits in patients with ovarian cancer (OS: HR = 0.67, 95% CI, 0.57 to 0.78, I2 = 76.5%, P <0.001; PFS: HR = 0.62, 95% CI, 0.53 to 0.73, I2 = 18.1%, P = 0.261)." (PMID 27690218, 2017). "Olaparib has recently been approved for ovarian cancer therapy by the FDA (in 4th line) and European commission (platinum sensitive) to treat patients with ovarian cancer resulting from hereditary BRCA1 or BRCA2 mutations." (PMID 29152107, 2017). "The purpose of this study was to examine proliferative and apoptotic activity in relation with BRCA1 expression in ovarian epithelial inclusions (OEIs), the putative precursor lesions of ovarian epithelial cancer (OEC)." (PMID 28270171, 2017). "A less-expensive BRCA1/2 testing tool would constitute a cost-effective strategy to further enhance control of breast and ovarian cancer in women with Colombian ancestry." (PMID 28680148, 2017). "At the age of 80, cumulative cancer risk for BRCA1 and BRCA2 mutation carriers ranges from 72% to 69% for breast cancer development, and from 44% to 17% for ovarian cancer." (PMID 29383107, 2017). "BRCA1 and BRCA2 germline mutations predispose to develop breast and ovarian cancer and also increases the risk to develop other cancer types including pancreatic cancer, prostate cancer, and melanoma." (PMID 28055979, 2017). "Although they have been associated with an increased risk of occurrence of various other types of cancer that are not of gynecologic origin, the majority of specific inherited mutations in BRCA1 and BRCA2 increase the risk of female breast and ovarian cancers." (PMID 29228641, 2017). "Mutations in the BRCA1 and BRCA2 genes lead to an increased risk of developing breast or ovarian cancer." (PMID 28751759, 2017). "Platinum-based therapeutics have been commonly used for treatment of ovarian cancer, and olaparib has recently been approved for the treatment of BRCA1/2 mutant ovarian cancer, with multiple trials on breast and other cancers ongoing or recently completed." (PMID 28398198, 2017). "BRCA1 and BRCA2 are essential for the repair of double-strand DNA breaks, and alterations in these genes are a hallmark of breast and ovarian carcinomas." (PMID 28099152, 2017). "Recently, genetic counselling and genetic testing of BRCA1 and BRCA2 for the presence of germline inactivating mutations have been increasingly offered to identify individuals at elevated risk of breast and ovarian cancer in Korea." (PMID 28351343, 2017). "To investigate the possible prognostic values of let-7e, BRCA1 and Rad51 in ovarian cancer, we first analyzed their correlation with the clinicopathological characteristics of EOC patients." (PMID 28376831, 2017).
ovarian carcinoma (continued). "Defects in BRCA1/2 promote the early development of breast and ovarian carcinomas, but also make cancer cells sensitive to DNA damage-inducing anti-cancer therapy and anti-PARP therapy." (PMID 28679437, 2017). "Multiplex ligation dependent probe amplification (MLPA) screening for LGRs in the BRCA1/2 genes was performed in index cases of 221 breast/ovarian cancer families." (PMID 28680148, 2017). "Patients characteristics of the healthy control group (wildtype and BRCA1) and patients tumor characteristics of the group of ovarian cancer patients (wildtype and BRCA1)." (PMID 29244844, 2017). "Germline mutations in BRCA1 and BRCA2 tumor suppressor genes are associated with an increased risk of breast and ovarian cancers." (PMID 28627138, 2017). "Women who are BRCA1 or BRCA2 mutation carriers face high lifetime risks of breast and ovarian cancer." (PMID 28624978, 2017). "Carrying a mutation in the BRCA1 or BRCA2 genes increases a woman’s lifetime risk of developing breast and ovarian cancer, although there are considerable differences in disease manifestation." (PMID 29383107, 2017). "Recent studies showed that results of the treatment with platins and PARP1 inhibitors in breast and ovarian cancers are dependant on the correlation between the increased expression levels of some miRNAs and a decrease in BRCA1 expression." (PMID 29021870, 2017). "We previously analyzed the entire coding regions of BRCA1/2 in patients with breast and ovarian cancer using the Ion AmpliSeqTM BRCA1/2 Panel, which is based on a PCR amplification method." (PMID 29383094, 2017). "To exclude the probable role of PTEN in the DDR, we chose the PTEN-null BRCA1 wild-type (WT) ovarian cancer cell line EFO-27 as our cell model." (PMID 28569838, 2017). "It has been shown that downregulation of BRCA1 gene expression in ovarian cancer cell lines increases their sensitivity to platinum treatment but leads to resistance to antimicrotubule agents." (PMID 29146938, 2017). "It is clear this topic is related to BRCA1/2 genes and their relationship to cancer, particularly breast and ovarian cancers." (PMID 28361690, 2017). "The first identified predisposition genes were BRCA1 and BRCA2 with a lifetime penetrance regarding ovarian cancer of 35–59% (BRCA1) and 11–17% (BRCA2), respectively." (PMID 29053726, 2017). "BRCA1 and BRCA2 germline mutation status is known to be associated with improved overall survival in ovarian cancer patients." (PMID 28831036, 2017). "The unweighted BRCA1- and BRCA2-specific PRS for breast and ovarian cancer, constructed on the basis of association results in CIMBA, showed strong evidence of association with breast and ovarian cancer (available online)." (PMID 28376175, 2017). "Inherited or acquired defects in HR, such as mutations in breast cancer susceptibility protein-1 (BRCA1) or BRCA2, predispose to cancer, including breast and ovarian cancers." (PMID 29145865, 2017). "Offering prophylactic surgery in BRCA1/2-positive women is the only effective option to decrease ovarian cancer mortality." (PMID 29053726, 2017). "NBR1 is originally cloned as a candidate gene for the ovarian cancer antigen and its position close to BRCA1, two isoforms of NBR1A and NBR1B are downregulated in malignant mammary tissues when compaired with normal cells." (PMID 29212269, 2017). "Germline mutations in BRCA1/BRCA2 significantly increase the risk of breast and ovarian cancer in women." (PMID 28780755, 2017). "In the ovarian cancer analysis, a statistically significant interaction with age was seen for the ovarian cancer PRS for BRCA1 carriers (P = .003)." (PMID 28376175, 2017). "Extensive research throughout the last few decades has revealed that mutations in BRCA1 and BRCA2, encoding essential proteins in the HDR pathway, are a critical component of HDR impairment in hereditary and sporadic breast and ovarian carcinomas." (PMID 28099152, 2017).
ovarian carcinoma (continued). "It is well known that BRCA1 and BRCA2 mutations are one of the known risk determinants for the development of ovarian carcinoma and BRCA1/2 mutations is associated with response to platinum-based chemotherapy." (PMID 28978132, 2017). "In Finland, strong founder effects and enrichment of deleterious alleles are seen and major founder mutations in BRCA1 and BRCA2 as well as in other breast and ovarian cancer susceptibility genes account for the vast majority of the identified mutations." (PMID 28874143, 2017). "The common characteristics of seven BRCA1 large genomic rearrangement cases were that they all have a family history of breast and/or ovarian cancer with at least one additional personal factor." (PMID 28205045, 2017). "Downregulation of BRCA1 in ovarian cancer provides sensitivity to platinum compounds while providing resistance to taxane drugs." (PMID 28008141, 2017). "BRCA1 and BRCA2 are the most well-known ovarian cancer susceptibility genes, with germline genetic testing available since the 1990s." (PMID 28250960, 2017). "Later research suggested that genetic testing for mutations in BRCA1 and BRCA2 be considered where there is a family history of either breast or ovarian cancer." (PMID 29262670, 2017). "BRCA1/2 genetic cancer testing helps to reduce breast/ovarian cancer incidence and increase life expectancy." (PMID 28570656, 2017). "Another study of 416 patients in Ontario with epithelial ovarian cancer found that only 19% of patients had undergone clinical genetic testing for BRCA1/2." (PMID 28250960, 2017). "The clinically available PARP1 inhibitors have shown considerable efficacy, especially in the treatment of breast and ovarian cancers, in patients with hereditary deletions of the HR BRCA1/2 genes." (PMID 28820388, 2017). "Decreased BRCA1 expression is associated with an improved response to treatment with PARP inhibitors and platinum based therapy in breast and ovarian cancer." (PMID 29021870, 2017). "By pooling the outcomes of 18,396 ovarian cancer patients from 34 individual studies, we found that BRCA mutation (BRCA1/2, BRCA1 and BRCA2) carriers had significantly improved OS and PFS benefits in ovarian cancer patients." (PMID 27690218, 2017). "Next, they separated the group of 218 wild-type BRCA1/2 ovarian cancers into a training and test set." (PMID 29021870, 2017). "Olaparib was the first PARP inhibitor to be approved by the EMA and FDA authorities for treatment of patients with BRCA1/2 mutant ovarian cancers." (PMID 28829366, 2017). "Women from families with a high incidence of breast and ovarian cancer (hereditary breast and ovarian cancer; HBOC) have increased risks of both these cancers, especially women with a germline mutation in the BRCA1 or BRCA2 genes." (PMID 28060958, 2017). "Germline BRCA1 and BRCA2 mutations account for about 10–15% of ovarian cancers and are mainly found in high-grade serous and endometrioid ovarian carcinomas." (PMID 28073364, 2017). "For individuals with BRCA1 and BRCA2 pathogenic variants, there is a significant risk for breast and ovarian cancer which correlates to the high frequency of contacting family members at genetic risk, both siblings and children." (PMID 28361098, 2017). "Other members of the FANCG complementation group include breast and ovarian cancer associated genes; FANCO (RAD51C), FANCS (BRCA1), BRCA2 (FANCD1), BRIP1 (FANCJ) and PALB2 (FANCN)." (PMID 28591191, 2017). "Women with BRCA1 or BRCA2 mutations, as well as women with family histories of breast or ovarian cancer, have an increased susceptibility to the risk-inducing effects of oral contraceptive usage." (PMID 28865460, 2017). "The breast and ovary cancer cases were similar for both genes with 7 and 6 cases for BRCA1 and BRCA2, respectively, while the 3 cases of male breast cancer (one bilateral) presented a mutation only in BRCA2." (PMID 28947987, 2017).
ovarian carcinoma (continued). "We selected the BRCA1-deficient ovarian cancer cell line UWB1.289 and the corresponding UWB1.289 + BRCA1 that expresses functional human BRCA1." (PMID 27375368, 2016). "The main indications for RRSO are risk-reducing surgery in women at risk of developing ovarian or fallopian tube cancer such as BRCA1 or BRCA2 germline mutations or hereditary (breast) and ovarian cancer (HBOC)." (PMID 26768420, 2016). "These cells are intrinsically resistance to physiological concentrations of cisplatin, raising the prospective of treatment failure for ∼50% of all ovarian cancer patients overexpressing BRCA1-IRIS." (PMID 27489859, 2016). "As per TCGA results, although 33% of ovarian cancer patients had alterations in BRCA, only a small proportion of patients showed mutations in both, BRCA1/2." (PMID 27385216, 2016). "A phase II clinical trial demonstrated that monotherapy with the PARP inhibitor olaparib (AZD-2281; AstraZeneca) achieved encouraging response rates of 41% and 33% in patients with BRCA1- or BRCA2-mutated advanced breast and ovarian cancers, respectively." (PMID 26967246, 2016). "A strength of our study is that the entire BRCA1/2 gene was screened for the first time in a population of women with epithelial ovarian cancer from Brazil, unselected for age and family history." (PMID 27914478, 2016). "In the present study BRCA1/2 mutations were identified in 58.8 % of patients with TNBC, who reported a family history of breast/ovarian cancer." (PMID 27553291, 2016). "BRCA1 and BRCA2 are the most important genetic susceptibility genes for breast/ovarian cancer in both Caucasian and Chinese populations." (PMID 26852015, 2016). "The first BRCA1 mutant patient displayed congenital abnormalities, inherited ovarian cancer and carboplatin hypersensitivity, but normal blood count." (PMID 27037238, 2016). "Germline mutations in the BRCA1 and BRCA2 genes greatly increase a woman’s risk of developing breast and/or ovarian cancer." (PMID 26852015, 2016). "Based on our results, the frequency of BRCA1 and BRCA2 mutations among Moroccan women with hereditary breast and/or ovarian cancer is 25.64 %." (PMID 27129401, 2016). "BRCA1 and BRCA2 are among the most frequently mutated genes in high-grade ovarian serous carcinoma, which is responsible for the vast majority of ovarian cancer deaths." (PMID 26745875, 2016). "Trial NCT02571725 which is about to open will be looking at combining olaparib with tremelimumab in BRCA1/2 positive patients with recurrent ovarian cancer." (PMID 27231574, 2016). "BRCA1/2 testing seems to have increasing role in clinical management in patients with advanced ovarian cancer who require treatment with poly(ADP-ribose) polymerase inhibitors." (PMID 26753012, 2016). "In this work we demonstrated that pre-cancer SOX2 overexpression in the FTE is nearly ubiquitous in HGSOCs and is also a common feature in women with BRCA1 and BRCA2 mutations prior to ovarian cancer initiation." (PMID 27492892, 2016). "Germ-line mutations in the tumour suppressor proteins BRCA1 and BRCA2 predispose individuals to breast and ovarian cancer." (PMID 27974137, 2016). "BRCA1 and BRCA2 mutations accounted for a considerable proportion of hereditary breast/ovarian cancer patients from eastern China and the spectrum of the mutations of these two genes exhibited some unique features." (PMID 26852015, 2016). "A total of 23 deleterious mutations of BRCA1 and BRCA2 were identified in 31 familial breast/ovarian cancer patients, and the frequency was 23.3 % (31/133)." (PMID 26852015, 2016). "More than a decade ago it was experimentally demonstrated in a human ovarian cancer cell line system that ID4 was a potent negative regulator of BRCA1." (PMID 27077368, 2016). "The mean age of ovarian cancer diagnosis was 54.5 (range: 36–76), 58.4 (range: 51–76) and 61.9 (range: 40–81) years for BRCA1, BRCA2 and wild‐type patients, respectively." (PMID 27167707, 2016).